LEP (leptin)
Diseases named in the same sentence as LEP in open-access papers (continued):
Sharing a sentence is not in itself a finding about the gene and the disease.
breast cancer (continued). "Leptin signaling, known to be associated with breast cancer aggressiveness and worse prognosis, activates transcription factors that upregulate VEGF/VEGFR2 to promote angiogenesis." (PMID 36074318, 2022). "In the current study, we recruited 1,616 participants including 963 breast cancer cases and 953 cancer-free controls to assess the correlation between LEP/LEPR polymorphisms and susceptibility of breast cancer." (PMID 35223490, 2022). "While leptin has pro-carcinogenic effects, adiponectin is inversely linked to breast cancer risk and aggressiveness." (PMID 33859943, 2021). "Increased leptin expression is significantly associated with increase post-menopausal breast cancer risk." (PMID 33482868, 2021). "Leptin increases the risk of breast cancer by increasing the effect of hormone secretion on breast tissue hyperplasia, which is more significant in postmenopausal women." (PMID 34485124, 2021). "On the contrary, data from meta-analyses showed an association between high leptin levels and higher breast cancer risk." (PMID 34209441, 2021). "Genotype distributions and allele frequencies of the leptin gene 2548G>A polymorphism in the group of women with breast cancer were 34% for WW, 47% for WV, 19% for VV, and in the group of healthy women it was 33% 43.5%, and 23.5% respectively." (PMID 33864589, 2021). "Further longitudinal studies are required to explain the relationship between LEP expression levels and the risk of breast cancer." (PMID 34414945, 2021). "The prior study has revealed that increased expression of leptin is associated with oncogenesis and progression of breast cancer." (PMID 34970222, 2021). "Next, the Kaplan-Meier model was used to analyze the association between estradiol, leptin, and prognosis of postmenopausal breast cancer patients in our cohort and the TCGA dataset." (PMID 34970222, 2021). "Despite the limitations of our study, specifically the small sample size and different cohorts for adiponectin and leptin measurements, we confirmed a significant increased risk of breast cancer for subjects with very low adiponectin levels." (PMID 34209441, 2021). "In females, higher leptin concentrations are associated with increased risk, as well as grade, stage and recurrence of breast cancer." (PMID 33987528, 2021). "Regarding adipokines, there exists a distinct relationship between leptin/adiponectin and breast cancer in postmenopausal women and such an association is far from clear in premenopausal women." (PMID 34485137, 2021). "High levels of circulating leptin in obese women have been linked to the increased risk and poor prognosis of breast cancer." (PMID 33763424, 2021). "Cancer-associated fibroblasts were observed to secrete leptin, which promoted the proliferation and migration of breast cancer." (PMID 34202922, 2021). "Previous single SNP association studies have found the same SNP alleles to be associated with lower odds of breast cancer in women, bone mineral density in older men, and to be trending toward association with plasma leptin levels in post-menopausal women." (PMID 34421692, 2021). "In both hepatoma and breast cancer cell lines, leptin causes cell cycle progression and adiponectin causes cell cycle arrest." (PMID 33530560, 2021). "The improved systemic adipocytokine profile (increased adiponectin:leptin ratio, increased omentin, decreased insulin) observed after only 12 weeks has implications for breast cancer risk and recurrence." (PMID 34638355, 2021). "Taken together, this explains the clinical observation that the increased levels of leptin and decreased adiponectin secretion are directly associated with breast cancer development." (PMID 35008370, 2021). "It is worth mentioning that the circulating levels of leptin increase proportionally to total adipose tissue mass and leptin has been identified as a key molecule in breast cancer risk and tumor biology." (PMID 34970222, 2021).
breast cancer (continued). "Leptin has an important role as an independent predictor of risk and prognosis of breast cancer, which has been correlated with its circulating levels." (PMID 34573003, 2021). "Higher serum leptin levels correlate with an increased risk of breast cancer as well as poor clinocopathological tumor characteristics in postmenopausal breast cancer patients." (PMID 34389732, 2021). "Like leptin, insulin is also a major risk factor for the development of breast cancer in postmenopausal women as it induces the activity of adipose aromatase." (PMID 33935708, 2021). "Our study aims to clarify the role of estradiol and leptin in breast cancer risk and prognostic assessment in postmenopausal Chinese women." (PMID 34970222, 2021). "In the last decade, our group has focused on the association of adiponectin and leptin with breast cancer." (PMID 34209441, 2021). "Circulating estradiol and leptin played important roles in the risk of postmenopausal breast cancer even in low-estrogen nations with an independent expression of ER status." (PMID 34970222, 2021). "Kaplan–Meier analysis indicated that elevated expression of leptin associated with poor overall survival in breast cancer patients (p = 0.003) with estrogen receptor (ER) positive breast cancer." (PMID 34389732, 2021). "In this context, it should be noted that generation and secretion of pro-inflammatory cytokines and adipokines, such as leptin and resistin, is higher in breast-cancer-associated adipocytes than in mature mammary adipocytes." (PMID 34681797, 2021). "An adipokine, leptin, has been implicated in breast cancer initiation via aromatase expression when the balance tips toward an excessive pro-inflammatory state." (PMID 34884317, 2021). "Next, we interrogated the association of miR-205, Med1 (PPARBP) and leptin with overall survival of breast cancer patients." (PMID 34389732, 2021). "Among several investigated adipokines that are associated with breast cancer, one of the most notable is leptin." (PMID 34063828, 2021). "In the mammary gland, the interaction between obese adipocytes and breast cancer cells leads to the transformation of mammary adipocytes into cancer-associated adipocytes (CAAs), which secrete more leptin and reduce the production of adiponectin." (PMID 33842335, 2021). "These elevated levels of leptin are associated with an increased risk of cancer, including kidney cancer, endometrial cancer, and breast cancer." (PMID 34202922, 2021). "Increased risk of colon cancer and breast cancer have been reported to link with high leptin levels." (PMID 34535145, 2021). "A significant association between plasma sex hormones and plasma leptin levels has been reported and previous studies have shown that postmenopausal women with breast cancer have higher concentrations of plasma leptin." (PMID 34554372, 2021). "High body mass index (BMI) is correlated with an increased production of hormones (estrogens, insulin, testosterone, leptin), and pro-inflammatory cytokines, which have been associated with breast cancer (BC) risk and recurrence." (PMID 34771702, 2021). "The LEP gene, which is the gene responsible for making Leptin, was found to be linked to many cancers mainly breast cancer, colorectal cancer, hepatocellular cancer and thyroid cancer." (PMID 33148191, 2020). "Previous studies have explored the role of inflammasome activation in the cell cycle mediated by leptin, and the authors found that leptin, a known risk factor for breast cancer, induces cyclin D1 expression and mediates cell cycle progression." (PMID 33613533, 2020). "As the molecular interplay between IGF1 and leptin, as well as its association with the pathogenesis of breast cancer, was shown previously, we have also analyzed the level of leptin which was significantly decreased in the group of MSC-CA." (PMID 32093026, 2020).
breast cancer (continued). "Collectively, these data demonstrate a positive association between FGFR1, leptin, and the LepR in human primary breast cancer and a much weaker association in metastatic tumors." (PMID 33019728, 2020). "Our findings are in line with previous studies, which demonstrated that leptin positively correlates with breast cancer risk, while a low adiponectin concentration is linked to a higher risk of breast cancer." (PMID 32512860, 2020). "Consistent with this, adipocyte-secreted leptin contributes to proliferation and migration of epithelial breast cancer cells, and is clinically associated with breast cancer malignancy." (PMID 32242230, 2020). "Leptin-deficient obese mice had decreased mammary tumor growth relative to wild type in syngeneic models, and leptin receptor (ObR)-deficient mice (with high leptin levels), showed greater mammary tumor growth with syngeneic cancer models." (PMID 33604295, 2020). "Other studies have indicated that a high leptin level is an important indicator of breast cancer risk in obese postmenopausal women." (PMID 32630445, 2020). "Hyperactive leptin signaling has been implicated in pathogenesis and metastases in gynecological and breast cancers by inducing cell proliferation and reduces cell apoptosis by activating c-myc in cervical cancer." (PMID 33050319, 2020). "From a clinical perspective and based on the adipokine-receptor principle, leptin/OBR was found to be closely associated with PAI-1 expression in breast cancer." (PMID 33371368, 2020). "Conversely, circulating LEP levels are positively associated with BMI and also breast cancer risk in some studies." (PMID 32046756, 2020). "Leptin seems to participate in the crosstalk between breast cancer cells and tumor-associated macrophages M2 by stimulating interleukin production to indirectly promote tumor breast cancer cell invasion and metastasis." (PMID 32260113, 2020). "The association between leptin signaling and breast cancer development has been previously examined." (PMID 32133259, 2020). "Leptin and its effects on the progression of breast cancer have also been implicated in the development of endocrine resistance." (PMID 33019728, 2020). "In this study, we leverage public gene expression datasets to evaluate the associations between FGFR1, leptin, and the leptin receptor (LepR) in breast cancer." (PMID 33019728, 2020). "In this study, we explored the effects of leptin on bone metastasis in breast cancer cells and underlying mechanisms." (PMID 32836215, 2020). "Studies on breast cancer patients have revealed an association between higher serum leptin levels and aggressive malignant tumour features." (PMID 32033341, 2020). "High body fat levels correlated with fasting insulin, leptin, triglycerides and inflammatory markers (IL-6, C-reactive protein), and increased breast cancer risk in postmenopausal women with normal BMI." (PMID 33604295, 2020). "A meta-analysis of 23 studies found that high leptin levels are positively correlated with the increased risk of breast cancer." (PMID 32630445, 2020). "Leptin produced by stromal cancer-associated fibroblasts promotes the invasion, migration, proliferation and mesenchymal transition of breast cancer cells." (PMID 33006013, 2020). "Leptin and its receptor are overexpressed in breast carcinoma especially in higher-grade tumors and are associated with distant metastasis and poor prognosis." (PMID 32727138, 2020). "People with high BMI together with high leptin/adiponectin ratio have a significantly higher risk of breast cancer incidence and metastasis." (PMID 31398937, 2019). "These mice, with an intact central leptin signaling and a deficient peripheral leptin receptor, exhibited a decreased mammary tumor growth and progression." (PMID 30634494, 2019). "Studies have established the association between the overexpression of leptin and its receptor, ObR, during breast cancer progression." (PMID 31554180, 2019).
breast cancer (continued). "In particular, leptin is an endocrine factor that is associated with obesity and induces breast cancer cell growth and invasiveness." (PMID 31052256, 2019). "Accumulating evidence has demonstrated that leptin is associated to the tumorigenesis and progression of breast cancer (BC)." (PMID 30702563, 2019). "That is probably why we didn’t see significant association between leptin and breast cancer risk in older women." (PMID 31292496, 2019). "Elevated leptin levels has been linked to breast cancer aggressiveness and bad prognosis in epidemiological studies." (PMID 31380268, 2019). "From an oncology perspective, high leptin levels appear to correlate with increased risk of certain cancers, including breast cancer." (PMID 31555578, 2019). "Distant leptin-derived metastatic in breast cancer is associated with 34% in the leptin receptor-positive patients, but none in the leptin receptor-negative patients." (PMID 31398937, 2019). "Clinical studies confirmed a positive association between serum leptin levels and breast cancer risk particularly in overweight/obese women." (PMID 31756890, 2019). "Currently more than 100 different adipokines have been identified, and among these, leptin and adiponectin have come to be recognized for their influence on breast cancer risk and tumor biology." (PMID 30634494, 2019). "Recent meta-analyses indicated an association between serum leptin levels and breast cancer risk particularly in overweight/obese postmenopausal women." (PMID 31336913, 2019). "Leptin has been linked to different stages and processes related to development and progression of breast cancer, involving the action of some mediators that participate in a more complex signaling transduction network." (PMID 31380268, 2019). "The data represented here contributes to the molecular characterization of the signaling events associated with leptin contributions to cell migration and invasion in breast cancer cell lines." (PMID 31671408, 2019). "Among women age <51 years, high leptin levels were significantly associated with decreased breast cancer risk (OR = 0.49, 95% CI: 0.24, 0.82)." (PMID 31292496, 2019). "In this sense, leptin promotes the synthesis of estrogen, which is related to an increased risk of breast cancer." (PMID 31380268, 2019). "Characteristics of included studies involving association between the serum leptin levels and breast cancer." (PMID 30702563, 2019). "Increased leptin levels in breast cancer patients have been linked with risk of metastasis and reduced survival." (PMID 30823902, 2019). "The overexpression of leptin and its receptor, the ObR, has been associated to tumor progression-related events in breast cancer." (PMID 31554180, 2019). "After adjustment for breast cancer risk factors, associations remained for the DNAm-predictors of cystatin C (HR: 1.37 95% CI: 1.16, 1.62, P<0.001) and leptin (HR: 1.12 95% CI: 1.03, 1.21, P=0.01)." (PMID 31848323, 2019). "Recently, other two studies further highlighted the potential role of leptin as a biomarker for breast cancer risk, especially in overweight/obese subjects and postmenopausal women." (PMID 30634494, 2019). "Oxidative stress is known to be involved in carcinogenesis, to modulate many cell signalling pathways and to be linked to inflammation, but data are sparse on how leptin affects oxidative stress in breast cancer." (PMID 30563501, 2018). "In the polymorphism of LEP G2548A, the associated allele A is the risk factor for the development of breast cancer, while, in the LEPR Q223R polymorphism, the R allele is linked to the development of the disease." (PMID 30404206, 2018). "The decrease in leptin in this and other weight loss interventions for breast cancer survivors exceeds the improvements identified with the use of Metformin." (PMID 29587682, 2018). "In vitro models have been used extensively to elucidate the mechanisms of leptin activation in biological processes associated with breast cancer progression." (PMID 30404206, 2018).
breast cancer (continued). "We firstly reported that leptin induces the expression of Notch family components in breast cancer, which was linked to IL-1 signaling." (PMID 30004402, 2018). "Circulating levels of leptin, a peptide hormone produced primarily by adipocytes that is overexpressed in breast cancer, were also associated with reduced premenopausal breast cancer risk in a prospective study, although not independently from BMI." (PMID 29931120, 2018). "Leptin promotes diverse biological events associated with essential processes of breast cancer such as EMT." (PMID 30404206, 2018). "Adipose-derived metabolic hormones, such as the adipokines leptin and adiponectin, modulate insulin sensitivity, activate NFkB and the mTOR pathway and are also associated with breast cancer risk." (PMID 29587682, 2018). "Increased ratios of adiponectin, leptin, and cytokines also promote inflammation, which creates a cancer-promoting environment; several cytokines are associated with poor breast cancer outcomes." (PMID 29804217, 2018). "Leptin was also shown to induce aromatase and this correlated positively with BMI, leading to increased risk for breast cancer." (PMID 30158901, 2018). "Elevated serum leptin levels and increased expression of leptin receptors is also reported in breast cancer patients that is often associated with higher pathological grade tumors and cancer treatment resistance." (PMID 30619088, 2018). "Data generated from obese mice hosting syngeneic mammary tumors showed leptin signaling induces Notch in vivo, which was linked to tumor growth and angiogenesis." (PMID 28659656, 2017). "Leptin can serve as a growth factor to induce breast cancer cell proliferation and has been associated with severity of breast cancer stage and metastasis." (PMID 27926517, 2017). "Recent studies in postmenopausal obese women and in obese and overweight breast cancer survivors following treatment suggest that weight loss decreases serum levels of leptin, insulin, and estrogens, and Ki67 expression in normal breast epithelial cells." (PMID 29187227, 2017). "Similar to the results of earlier analyses, our results also show that leptin levels are associated with increased risk of breast cancer." (PMID 29088874, 2017). "In the present study, we investigated the molecular mechanisms underlying leptin-induced growth of breast cancer cells, with focus on the role of ER signaling in relation to autophagy induction." (PMID 29312618, 2017). "Accumulating evidence strongly suggest that high levels of leptin and OB-R found in tumor tissues are associated with metastasis and decreased survival rates of breast cancer patients." (PMID 28659656, 2017). "Leptin caused a significant dose-dependent increase in cell viability in MCF-7 breast cancer cells after 48 h incubation." (PMID 28930270, 2017). "Our results imply that leptin is a more effective indicator of breast cancer risk in postmenopausal women than premenopausal women." (PMID 29088874, 2017). "Herein, we demonstrated that E2F1 suppression by autophagy induction is closely associated with leptin-induced cell cycle progression in breast cancer cells." (PMID 29312618, 2017). "In fact, in our experience, a low Leptin level is associated with an healthy status (OR:0.23; 95% CI 0.06–0.76); however, also in our experience, the strongest predictive factor for breast cancer development resulted an older age." (PMID 29254161, 2017). "Leptin plasma levels are increased in obese subjects and higher leptin levels are associated with an increase in breast cancer risk." (PMID 29271901, 2017). "To date, accumulating evidence indicates that increased serum levels of leptin and decreased adiponectin are associated with breast cancer risk." (PMID 28178355, 2017). "Based on previous reports, it is well established that higher levels of circulating leptin contribute to the development and/or progression of breast cancer and that ER signaling is implicated in leptin-induced tumor growth." (PMID 29312618, 2017).